IL1B (interleukin 1 beta)
Diseases named in the same sentence as IL1B in open-access papers (continued):
Sharing a sentence is not in itself a finding about the gene and the disease.
infection (continued). "In comparison to uninfected mice, the levels of IL-1β, IL-6, IL-12p70, TNF-α, CCL2, CXCL2, GM-CSF, and G-CSF were significantly increased in both PLF and serum after infection." (PMID 38951957, 2024). "Spinal cords of wild-type mice contained significantly higher levels of IFN-β and IL-6 at day 5 post-infection (p ≤ 0.05) and IFN-γ, IL-1β, CCL3, CCL5, and CXCL9 at 5 and 9 days post-infection (p ≤ 0.05)." (PMID 39339840, 2024). "The iNOS is one of nitric oxide synthesis (NOS) enzymes that catalyzes NO production, and COX-2 regulates the production of NO and pro-inflammatory cytokines such as IL-6, IL-1β, and TNF-α to facilitate pathogen clearance during infection." (PMID 38213288, 2024). "During infections with viruses like influenza and SARS-CoV-2, the host’s immune response can lead to pyroptosis in infected epithelial cells, releasing cytokines like IL-1β and IL-18, which further recruit immune cells and intensify inflammation." (PMID 39770727, 2024). "As ITA is an immunomodulatory agent, we measured the pro-inflammatory cytokines TNF, IL-6, and IL-1β, and the anti-inflammatory cytokine IL-10 in cell culture supernatants 24 hours after NMII infection of Acod1+/- and Acod1-/- BMM." (PMID 39156902, 2024). "At 5 days after inoculation, the mRNA expression levels of TNF-α, IL-12, and CXCLi1 were more significantly increased (p < 0.01), and the increased expression of IL-1β and IFN-γ was also observed at 5 days post-infection (p < 0.05)." (PMID 38846788, 2024). "We observed a decrease in IL-1β, IL-6, TNF, and IFNβ levels in the supernatants of GSDMD knockdown (KD) macrophages despite comparable levels of infection as indicated by viral nucleoprotein levels in Western blots." (PMID 38553499, 2024). "Direct infection of the atherosclerotic plaque by SARS-CoV-2 produces an enhanced inflammatory response with the release of cytokines such as IL-6 and IL-1β, which are key to the formation of a plaque." (PMID 38541641, 2024). "We observed significant increases in proinflammatory cytokines IL-6 and IL-1β in the lungs of 5-LO−/− mice, compared to levels in C57BL/6 mice, at day 7 post-infection." (PMID 39082787, 2024). "There has been extensive work using cell lines and mast cells derived from human cord blood that has shown FcγRII-dependent enhancement of infection, upregulation of CCL3, CCL4, CCL5, IL-1β, and IL-6, and TNF-α-mediated endothelial activation." (PMID 38793609, 2024). "In vitro, CrT1 function (Na+-dependent 14C-Cr uptake), expression and promoter activity significantly decreased following TNFα/IL1β treatments and AIEC infection." (PMID 38928243, 2024). "Inflammatory cytokines (such as IL-1β and TNF-α) in the PAMs infected with Del4L showed a significant increase compared with ASFV-WT infection at 12 and 20 hpi." (PMID 38501350, 2024). "While TNFA, IL1B, and TLR2 expression was significantly dampened upon both Mtb HN878 and Mtb CDC1551 infection, expression of MCP1 was significantly upregulated by these infections in macrophages trained and restimulated with BCG, LPS, or hk-CDC." (PMID 38980014, 2024). "IL-1β was elevated specifically in the TBI-Kp group, suggestive of an additive effect of TBI and infection for this mediator." (PMID 38720343, 2024). "We found that TNF-α, IL-β, CXCL2, TLR4, and IL-6 (mRNA) and selected proteins (TNF-α, IL-1β, and CXCL2) were upregulated significantly by exposure to the particulate and infection." (PMID 38928968, 2024). "This intervention involves inhibiting the inflammasome pathways, which play a pivotal role in the production of IL1β and IL18 cytokines during infections by M. tb." (PMID 39125766, 2024). "In vivo experiments in mice of catheter-induced S. aureus infection showed a significant reduction in cytokine secretion of IL-1β, TNF-α, CXCL2, and CCL2 during biofilm infection." (PMID 38571946, 2024).
infection (continued). "Not surprisingly, animals deficient for COX2 showed a strong increase in viral titers in the lung after infection with influenza A virus, whereas the concentrations of cytokines such as TNF, IL-1β, IL-6 and IFNγ were reduced in bronchoalveolar lavage fluid." (PMID 39107476, 2024). "Inflammatory cytokines, including interleukin 6 (IL-6), interleukin 1β (IL-1β), and tumor necrosis factor-alpha (TNF-α) are secreted by microglia within the brain in response to injury and infection." (PMID 39000602, 2024). "We have shown previously, in our combined in vitro and in vivo study, that THP-1 cells infected with live and heat-killed T. forsythia were the most potent inducers of IL-1β and TNF compared to polymicrobial infection." (PMID 38003583, 2023). "Quantification of viral release to supernatants harvested at 24 h post-infection revealed ~350-fold lower virus titers in cells pretreated with IFN-γ and ~700-fold lower virus titers in cells pretreated with IFN-γ plus IL-1β in comparison to media alone." (PMID 38162653, 2023). "To assess the immunological response of C57BL/6J- Cftrtm1UncTg(FABPhCFTR)1Jaw/J mice to S. maltophilia and P. aeruginosa polymicrobial infection, we measured inflammatory markers in the BALF by multiplex assay for IL-1α, IL-1β, IL-6 and TNF-α." (PMID 36748431, 2023). "Inflammatory MoDCs are multifunctional and express IL-1α, IL-1β, IL-10, TNF-α, and inducible nitric oxide synthase (iNOS) in the lungs between 2 and 3 weeks after infection with M. tuberculosis." (PMID 37686061, 2023). "Few genes were modulated at 31 dpi in gastrohepatic lymph nodes from animals that survived after infection with the culture-adapted strain E75CV1: three upregulated (IFN-γ, IL-23, NFκβ) and two downregulated (IL-1β, IL-4)." (PMID 36680273, 2023). "For example, following C. albicans fungal brain infection, microglia produced IL-1β and CXCL1 within 24 hours of infection, which elicited a significant influx of neutrophils to the brain to enable clearance of the infection." (PMID 37938547, 2023). "By quantitative RT-PCR (qRT-PCR), we confirmed that IL-6, IL-1β, and MMP-8 mRNAs were commonly upregulated in the liver and small intestine after infection and were all suppressed by anti-TNF-α Ab treatment." (PMID 37939119, 2023). "We analyzed the effect of PACAP pre-treatment on pro-inflammatory cytokines IL-1β, IL-6, TNF-α, and IFN-γ in RTS11 cells after challenge with Y. ruckeri at day 3 post-infection (day 4 after PACAP exposure)." (PMID 37887185, 2023). "After infection of THP-1 with BCG (MOI = 10) for various time intervals, TNF-α and IL-1β transcripts were significantly upregulated in a time-dependent manner." (PMID 36788275, 2023). "Histopathology and inflammatory genes (Nos2, Il-1β, Tnf-α, and Cxcl1) were elevated and persisted in the large intestine of muMT mice compared with WT mice during chronic ETBF infection." (PMID 38203534, 2023). "PSMB8 overexpression reduces the virus-induced activation of NF-κB promoters and suppresses the expression of proinflammatory IL-1β, TNF-α, IL6, IL8, and IFN-γ upon infection with nerve necrosis virus." (PMID 38031182, 2023). "When infection or inflammation is severe enough to affect an organ, macrophages can first exhibit the M1 phenotype to release TNF-α, IL-1β, IL-12, and IL-23 against the stimulus." (PMID 36636989, 2023). "Following secretion of chemokines and cytokines such as IL-1β, IL-6, TNF-α, IL-21, and IL-8, the SARS-CoV-2-induced cytokine storm and hyperinflammatory response have pivotal roles in infection severity, AKI development, and death." (PMID 37026010, 2023). "The whole process was driven by infection of mice with Clostridium difficile (C. difficile) to induce NLRP3 inflammasome leading to pyroptosis and IL-1β release through pore forming GSDMD." (PMID 38087059, 2023). "In analyzes of lung homogenates 3 days post infection, BALB/c mice had higher protein levels of IP-10, IL-1β, TNF-α, M-CSF, IL-4, IL-12, IL-15 and IL-17." (PMID 36810092, 2023).
infection (continued). "The mRNA levels of IL-1β and TNF-α in lungs were all significantly down-regulated by the melatonin administration at day 6 and/or day 9 post-infection compared to the infected control mice (P < 0.05)." (PMID 37200384, 2023). "Compared to B lineage isolates, infection of mice with UT21 had lower levels of CCL2, CCL3, CCL4, TNF-α, and IL-1β." (PMID 36992320, 2023). "Infection of BV2 cells with JEV resulted in significant higher expression of IL-6, TNF-α, MCP-1 and IL-1β as compared to un-infected cells." (PMID 36707891, 2023). "In the present study, infection with F. necrophorum significantly increased the expression of TNF-α, IL-8, and IL-1β, and these inflammatory cytokines further mediated the inflammatory response of the cow intertoe skin." (PMID 37153149, 2023). "The levels of IL-1β, IL-6 and IP-10 were significantly reduced in the spleens of STING KO mice at 7 and 14 days after intratracheal infection." (PMID 37261352, 2023). "Collectively, these data implicate that in a multi-cellular infection model (3D), CBD and HU308 can decrease viral RNA levels, and that HU308 can reduce IL-1β and TNF-α proinflammatory cytokine mRNA levels." (PMID 37631062, 2023). "When bacteria and other pathogens enter our body, macrophages secrete inflammatory mediators including NO, PGE2, and proinflammatory cytokines (IL-6, IL-1β, and TNF-α) that attract immune cells to the site of infection and activate cells to eliminate them." (PMID 37513335, 2023). "Our results show that the infection of mice with SARS-CoV-2 induces the expression of several pro-inflammatory CC and CXC chemokines activated through NF-κB but weakly IL1β and IL18 whose expression are more characteristic of inflammasome formation." (PMID 36851549, 2023). "In the present study, we evaluated the immunogenicity and protective efficacy of mucosal delivery of Ad-HA/NP+Ad-IL-1β to heterologous H3N2 challenge in pigs and compared this to heterotypic protection induced by a prior infection with pH1N1." (PMID 37153548, 2023). "Infection with virulent ASFV isolates often results in exacerbated immune responses, with increased levels of serum pro-inflammatory interleukins (IL-1α, IL-1β, IL-6), TNF and chemokines (CCL2, CCL5, CXCL10)." (PMID 36680273, 2023). "In conclusion, we demonstrated that infection with IAV leads to the establishment of a pro-inflammatory milieu in the lungs via the infiltration of neutrophils that secrete mature and bioactive IL-1β." (PMID 37958758, 2023). "Using commercial ELISA kits, levels of IL-1β and TNF were also evaluated in serum samples taken from euthanized pigs at different days after infection." (PMID 36680273, 2023). "RT-PCR data showed that the titers of all three inflammation-related genes (IL-6, IL-1β, and TNFα) were upregulated upon SARS-CoV-2 Delta-spike PV infection and decreased upon treatment with compounds K-4 and M-4." (PMID 36855173, 2023). "Markers IL-1β, IL-6 and TNF-α also decreased following polymicrobial infection as compared to single-species P. aeruginosa infection, which was significantly higher than uninfected controls (****P<0.0001)." (PMID 36748431, 2023). "Infection of APCs with opsonized EBs enhanced expression of chemokines CXCL1, 2, 5 and pro‐inflammatory cytokines IL1β and IFNγ and TNF mRNA." (PMID 38441219, 2023). "In neonatal mice, inflammatory Ly6C+ monocytes recruited into the subepithelial intestine and macrophages are shifted to a proinflammatory phenotype during infection, produce TNF-α and IL-1β." (PMID 37325809, 2023). "Immunoglobulin (IgG) and cytokine (IL-1β, IL-6, IL-10, IFN-γ) levels were determined in ewes’ plasma collected before infection and at parturition, in lambs’ plasma at 24 and 72 h after their birth, and in colostrum samples at parturition and 72 h later." (PMID 37508158, 2023). "Increased expression of TNF-α, IL-1β, and IL-6 was seen predominantly with DENV2 infection and at higher levels with Mon601 compared with DENV1 and DENV2 field isolates." (PMID 37515098, 2023).
infection (continued). "To determine if PAM-Tang cells exposed to S. suis have the ability to secrete pro-inflammatory cytokines, we used ELISA kits to detect the pro-inflammatory cytokines IL-18, IL-1β, and TNF-α secreted by PAM-Tang cells at different times post-infection." (PMID 36677452, 2023). "In the HLN of primoinfected sheep, Th1 related cytokines (IL-1β and TNF-α) were overexpressed at early stages of infection, while in reinfected sheep these two cytokines were highly expressed in late stages." (PMID 36627694, 2023). "As for the source of IL-1β, it has been shown that activation of the NLRP3 inflammasome by infection with either Chlamydia muridarum or Haemophilus influenzae and subsequent activation of caspase 1 leads to the enhanced release of IL-1β." (PMID 37759430, 2023). "Treatment of mice with DSS and infection with parasites resulted in increased levels of IL-6, TNF-α, and IL-10 in serum; IL-1β and IL-6 in the colon; and IL-6 in the small intestine." (PMID 36836678, 2023). "M1 macrophages produce pro-inflammatory cytokines, such as IL-1β, IL-6, IL-12, and TNF-α, which help to activate and recruit other immune cells to the site of infection or tissue injury." (PMID 37507898, 2023). "Regarding cytokine production, ELISA analysis further demonstrated that both cKp and hvKp infection greatly enhanced the release of IL-6, TNF-α, and IL-1β in macrophages." (PMID 37223846, 2023). "As a result, more T. marneffei were detected in TUT1-overexpressing THP-1 macrophages at 24 h post-infection, and pro-inflammatory factors (TNF-α, IL-1β) were down-regulated at 24 h post-infection." (PMID 37845378, 2023). "ELISA measurements indicated enhanced expression of CCL28, IL-1β, IL-6, and TNF-α following infection with Adv-CCL28, compared with Adv-Ctl." (PMID 36713846, 2023). "We analyzed hLO culture supernatants for the presence of ten cytokines and chemokines commonly produced by epithelial cells in response to infection (TNF-α, IFN-α2a, IFN-β, IFN-λ1, IL-8, IL-1α, IL-1β, IL-6, IP-10, MCP-1)." (PMID 37883246, 2023). "Among the cytokines, IL-1β, IL-6, and IL-18 are known to be very important cytokines that respond to a PAK infection [36, -38]." (PMID 36788468, 2023). "Surprisingly, a weak, but significant SARS-CoV-2-MOI-dependent release of IL-1β was detected in response to Caco-2 and ACE2-A549 infection during 24 hours." (PMID 37920468, 2023). "Inhibited caspase-1 activation and IL-1β production in in vitro SARS-CoV-2 infection of primary human monocytes and reversed lung pathology in a mouse model of infection but increased the release of virus from macrophages." (PMID 36661317, 2023). "We found that PRV-infection induced significantly higher transcriptional levels of TNF-α, IL-1β and IL-6, and that DMY-treatment exhibited significantly lower mRNA levels of these cytokines." (PMID 36851415, 2023). "The inflammatory response of the body after infection requires the initiation of the NF-κB signaling pathway, and the inflammatory factors TNF-α and IL-1β activate NF-κB, which regulates the production of the Bcl-2 anti-apoptotic protein." (PMID 37570890, 2023). "When infection and cellular injury occur, the NLRP3 inflammasome can activate caspase-1 and then induce the activation of the inflammatory cytokines IL-1β and IL-18." (PMID 36713830, 2023). "The naïve infection control group showed the highest levels of IFN-γ, TNF-α, IL-6, and IL-1β cytokines in lung samples at 6 days after infection." (PMID 37515025, 2023). "We report that during infection of macrophages and dendritic cells with various intracellular bacteria, XIAP restricts cell death and secretion of IL-1β but promotes increased activation of NFκB and JNK which results in elevated secretion of IL-6 and IL-10." (PMID 37347786, 2023). "In contrast, infection with IPTG-treated BL21/pEhaF resulted in a marked decrease in IFNβ, IL-6, and IL-1β demonstrating that in trans expression of EhaF is sufficient for the innate immune inhibition." (PMID 37041208, 2023).
infection (continued). "Importantly, infection of neutrophils with engineered mutant strains of P. aeruginosa in which ExoS has been inactivated induced significant levels of pyroptosis associated with IL-1β release in wildtype, but not in caspase-1-deficient neutrophils." (PMID 37939552, 2023). "Taken together, the downregulated TNF-α and IL-1β secretion by PRRSV in immune and PGE cells reflects a poor innate immune response which leads to secondary infection by other microbial pathogens." (PMID 37099541, 2023). "We found that infection of zebrafish larvae with LD or HD of WT-GFP induced a rapid (by 6 hpi) and robust induction of il1b and tnfa gene expression." (PMID 37155695, 2023). "Another targeted transcriptomic study of PJI-associated periprosthetic tissues found elevated levels of granulocyte colony-stimulating factor (G-CSF), IL-1β, IL-6, IL-8, and CD40L at infection sites." (PMID 36830206, 2023). "We thus compared the expression levels of proinflammatory cytokines Tnf, Il6, Il1b, and the anti-inflammatory cytokine Il10, in the lung tissues between the DMI-treated and vehicle-treated control mice during infection." (PMID 36882813, 2023). "Infection with KSHV induces high levels of pro-inflammatory cytokines, chemokines and angiogenic factors such as TNF, IL-1α, IL-1β, IL-6, CXCL8, IFN-γ, VEGF, COX-2 and GM-CSF." (PMID 36634147, 2023). "The levels of IL-12p70, MCP-1, IL-10, IL-1β, IFN-γ, IL-2, M-CSF, VEGF, ICAM-1, and P-selectin increased after infection; however, the expression of all except MCP-1, IFN-γ, and P-selectin was strongly suppressed by anti-TNF-α Ab treatment." (PMID 37939119, 2023). "Mechanistic studies using an in vitro human tonsil organoid infection model revealed that HIV infection of T cells also resulted in increased polyamine synthesis, which was dependent on the activities of caspase-1, IL-1β, and ornithine decarboxylase-1." (PMID 36693889, 2023). "Significantly elevated Sphk1 and Il-1β in the UFP-PR8 group are positively correlated with viral titer and infection severity." (PMID 37069680, 2023). "Consistent with the results of in vitro studies, Del2R infection induced higher levels of IL-1β and TNF-α production with significantly reduced replication in pigs compared with ASFV-WT infection." (PMID 37566637, 2023). "Infection with ply+lytA+ strain A66 induced detectable IFNγ, IL-6, TNFα, RANTES, IL-1α and IL-1β in the lungs of inoculated mice, and all but IL-1α in the bloodstream." (PMID 36897919, 2023). "Inflammatory mediators including IL1β, TNF, and IL6 displayed significant differential secretion across the time points, indicating their contribution to a pro-inflammatory reaction to infection." (PMID 37333188, 2023). "A previous study found that the inflammation-related cytokine genes IL-1β, IFN-α, TNF-α and NF-κB in the blood had a higher over-expression after infection with C. perfringens type C." (PMID 36975519, 2023). "The levels of interleukin (IL)-6, IL-1β, and tumor necrosis factor α (TNF-α) after infection with ΔadcAΔlmb at 9 and 12 h were significantly lower than those after WT infection." (PMID 37212676, 2023). "By performing H&E staining and ELISA at 7 days post-infection (dpi), we found that Sept2fl/flLyz2-Cre mice showed more severe inflammation in the lungs and higher cytokine levels of TNF-α, IL-1β, IL-6 and IL-12 p40 in the BALF than control mice." (PMID 37978190, 2023). "In summary, our model shows elevated IL-1β, IL-6 and CXCL8 mRNA levels after 24 h infection with PA." (PMID 37432929, 2023). "Infection of BMDCs with EBs opsonized with male IgG enhanced expression of chemokines CXCL1, CXCL2, CXCL5 and pro‐inflammatory cytokines TNF, IL1β and IFNγ compared to uninfected or non‐opsonized controls." (PMID 38441219, 2023). "In the present study, we report that infection with BCG significantly induces macrophage apoptosis and induces the production of DUSP1, TNF-α and IL-1β." (PMID 36788275, 2023).